LGALS3 (galectin 3)
Diseases named in the same sentence as LGALS3 in open-access papers (continued):
Sharing a sentence is not in itself a finding about the gene and the disease.
Stroke (continued). "Moreover, galectin-3 had a good predictive ability for the prognosis of stroke." (PMID 36846691, 2023). "AZ_628, which screened from CMap analysis, was found to have lower binding energy with Mmp12, Lgals3, Fam20c, Capg, Pkm2, Sdc4, and Itga5 in microglia subcluster 2 and maybe a therapeutic agent for the poor development of microglia subcluster 2 after stroke." (PMID 38067435, 2023). "Thus, we also investigated the joint effects of sTREM2 and galectin-3 on clinical stroke outcomes." (PMID 35414082, 2022). "The prognostic value of galectin-3 in stroke might be involved in the Inflammation pathway." (PMID 33686023, 2021). "Thus, the implications of increased expression of Lgals3 at 4 or 8 weeks after stroke may include two aspects: the chronic inflammatory response and the protective effect induced by IGF-1 production after stroke or brain injury." (PMID 31888302, 2019). "Toward this goal, the current study explores the function of Galectin-3 (GAL3) in MDMø and elucidates mechanisms whereby MDMø-derived GAL3 exacerbates stroke injury." (PMID 41701549, 2026). "The median serum level of galectin-3 in those included patients was 7.3ng/ml (IQR, 5.1-11.6), with higher levels indicating increasing stroke severity." (PMID 33686023, 2021). "In proliferating microglia there is co-expression of Galectin-3 and Insulin-like growth factor 1 (IGF-1), while in Galectin-3 KO C57Bl/6 mice there increased protein level of IGF-1 after stroke." (PMID 32455781, 2020). "In adult stroke models, galectin-3-positive microglial cells also produce neurotrophic factors, such as IGF-1, which also protect against damage after stroke." (PMID 31888302, 2019). "The high expression of LGALS3 in the MG2 microglial cell subset, which predominates early after stroke, suggests its potential role in promoting a pro-inflammatory environment, whereas MG0, in its resting state, may exert a protective effect." (PMID 40458459, 2025). "Discrimination, calibration, and reclassification after the addition of galectin-3 and hs-CRP to the conventional clinical risk model on the composite of all-cause mortality, non-fatal MI, and stroke." (PMID 40747494, 2025). "Nonetheless, in a separate study, secreted galectin-3 was shown to act as a ligand for the toll-like receptor 4 (TLR4) and promote inflammatory response in a murine neuroinflammatory LPS model and in the brain of stroke patients." (PMID 29867350, 2018). "In addition, we show in human stroke that pericytes express RGS5 and co-express the macrophage/microglial marker galectin-3 (GAL-3)." (PMID 24848101, 2014). "Besides, galectin-3 and soluble ST-2 were significantly higher in patients with stroke and AF compared to patients with stroke without AF." (PMID 35845077, 2022). "Importantly, subsequent PPI network analysis revealed that an inflammation-related protein named galectin-3 (LGALS3) could be tightly networked with other proteins and serve as a key player of QSYQ action at the subacute phase of stroke." (PMID 33953667, 2021). "We could not assess when and how long galectin-3 was changed in stroke patients." (PMID 33686023, 2021). "The incidence of all-cause mortality, cardiac mortality, composite of cardiac mortality, non-fatal MI, and stroke, and composite of MACE was significantly higher in patients with high galectin-3 than in those with low galectin-3." (PMID 40747494, 2025).
coronary artery disease (78 papers, 2012 to 2026). "Recent studies have implicated galectin-3 in many chronic diseases, including coronary artery disease (CAD), heart failure (HF), CKD, and atrial fibrillation." (PMID 38195853, 2024). "High serum and plasmatic galectin-3 levels are also associated with the severity of coronary stenosis in patients with coronary artery disease." (PMID 36873388, 2023). "Galectin-3 (Gal-3) is a new independent risk factor in the development and severity of coronary artery disease (CAD)." (PMID 32485853, 2020). "The aim of this study was to elucidate the association between LGALS3 genotypes, galectin‐3 levels, and inflammatory marker levels in patients with coronary artery disease (CAD)." (PMID 32573962, 2020). "Galectin-3 has been associated with coronary artery disease (CAD) and CV death in high-risk patients referred for coronary angiography." (PMID 31752995, 2019). "Galectin-3 has also been demonstrated to be associated with unstable atherosclerotic plaques; individuals with unstable coronary artery disease had higher galectin-3 concentrations than those with stable coronary artery disease." (PMID 36673621, 2023). "Besides, one study showed that galectin-3 was associated with cardiovascular death in coronary artery disease patients." (PMID 33686023, 2021). "Galectin-3 may one day allow identification and treatment of patients with coronary artery disease with a major risk of cardiomyopathy development." (PMID 25960597, 2015). "In multivariate linear regression analysis, significant independent predictors of higher galectin-3 values were older age, presence of coronary disease, hypoventilation syndrome, higher BMI, NTproBNP, lactate, creatinine, lower LDL, and lower FEV1 (p < 0.05)." (PMID 39941305, 2025). "The significant independent predictors of higher galectin-3 values were older age, presence of coronary disease, hypoventilation syndrome, higher BMI, NTproBNP, lactate, creatinine, lower LDL, and lower FEV1." (PMID 39941305, 2025). "Elevated levels of galectin-3 have been detected in the plasma of coronary artery disease patients, where it enhances platelet activation and promotes thrombus formation." (PMID 40149705, 2025). "Patients in the high galectin-3 group were older (70.2 ± 12.7 versus 67.0 ± 12.6 years; P = .040) and had a higher prevalence of pre-existing coronary artery disease (CAD; 28.2% versus 11.7%; P = .001)." (PMID 41158187, 2025). "Since CAC is a reflection of severity of coronary heart diseases, we evaluate the predictive value of galectin-3 on CAC." (PMID 35685493, 2022). "In human patients with heart diseases, including coronary heart disease, HF, and atrial fibrillation, increased circulating galectin-3 has been reported." (PMID 34722704, 2021). "We concluded that galectin-3 expression levels and LGALS-3 (rs4652) AC genotype were coronary artery disease risk factors in people with type two diabetes among an Egyptian sample." (PMID 34616230, 2021). "We aimed to elicit the pro-inflammatory effect of galectin-3 as determined by interleukin-6 (IL-6) serum levels and to explore the relationship between galectin-3 (LGALS-3 rs4652) gene variant and its expression levels with coronary artery disease (CAD) risk among T2DM Egyptian patients." (PMID 34616230, 2021). "Galectin-3 is also associated with the risk of developing HF after acute coronary syndrome and supports potential clinical relevance of galectin-3-related pathway in patients with ischemic heart disease." (PMID 25960597, 2015). "Galectin-3 could be used as an additional tool for diagnosis and severity assessment of atherosclerotic disease in patients with suspected coronary artery disease." (PMID 40747494, 2025). "We hypothesized that galectin-3 and pentraxin-3 levels, along with inflammatory indices, would differ according to coronary artery disease severity and arrhythmia presence, reflecting their potential utility in risk stratification." (PMID 40430046, 2025).
coronary artery disease (continued). "A high concentration of galectin-3 was observed in coronary heart diseases and MI patients." (PMID 35685493, 2022). "Galectin-3 was associated with cardiovascular events in diabetics with coronary artery disease, whereas NT-proBNP predicted events in patients without T2DM35." (PMID 34561496, 2021). "This study aimed to investigate the possible role of serum galectin-3 (Gal-3) levels in the diagnosis and assessment of significant epicardial artery lesions in patients with suspected coronary artery disease (CAD)." (PMID 37221462, 2023). "The absence of a significant association between LGALS3 gene variants and the inflammation markers levels suggested that it should be cautious when galectin‐3 was used as a therapeutic target for chronic inflammatory disorders, such as coronary artery disease." (PMID 32573962, 2020). "Nevertheless, there are novel evidences that connect galectin-3 and ST2 with coronary heart disease and, specifically, with atrial fibrillation." (PMID 34439833, 2021). "Its pathophysiologic association with inflammation, cell proliferation, and fibrogenesis may implicate serum galectin-3 as a predictor of clinical outcomes in coronary artery disease (CAD) patients undergoing percutaneous coronary intervention (PCI) with drug-eluting stents (DES)." (PMID 40747494, 2025). "The relationship between galectin-3 (Gal-3) and coronary artery disease (CAD) has not been fully elucidated." (PMID 35198615, 2022). "Nonetheless, another study demonstrated galectin-3 did not independently predict recurrent CV events in patients with established coronary heart disease after adjusting markers of hemodynamic stress, myocardial injury, inflammation, and renal impairment." (PMID 30249969, 2018). "Additionally, a recently published study demonstrated that Gal-3 levels, but not LGALS3 genotypes, were associated with multiple inflammatory marker levels in patients with coronary artery disease." (PMID 35807161, 2022).
colon carcinoma (77 papers, 2005 to 2025). "High galectin-3 expression is observed in many forms of cancer, including thyroid, pancreatic, and colon cancers, and has been linked to cancer progression and metastasis." (PMID 28593065, 2017). "In colonic cancers, nuclear localization of galectin-3 is associated with resistance to 5-fluorouracil (5-FU) treatment." (PMID 22039439, 2011). "The expression of galectin-3 is associated with tumor invasion and metastatic potential in head, neck, thyroid, gastric and colon cancers." (PMID 22024187, 2011). "This study reports that suppression of C1GalT1 expression in human colon cancer cells caused substantial changes of protein glycosylation of cell membrane proteins, many of which were ligands of the galactoside-binding galectin-3 and the macrophage galactose-type lectin (MGL)." (PMID 37612278, 2023). "Galectin-3, which is widely expressed in normal and tumor cells, is associated with cell growth, adhesion, differentiation and death, and has been observed to be expressed in colon cancer, gastric cancer and other malignancies." (PMID 25373317, 2015). "Galectin-3 is a β-galactose binding protein, which may participate the process of the cell growth, adhesion, inflammation, immune-regulation and apoptosis, and therefore associated with the formation and metastasis of many tumors, such as colon cancer and PTC." (PMID 30005075, 2018). "A similar study demonstrate that not only galectin-3 but also galectin-1 expression levels correlate with the degree of dysplasia, suggesting that galectin-1 is related to malignant progression, while galectin-8 has been associated with suppressor activity in colon cancer." (PMID 23658855, 2010). "The study from 2023 revealed an important mechanism in promoting Galectin-3-mediated cancer progression and metastasis in colon cancer." (PMID 40507492, 2025). "In a more recent study, cardiac mesenchymal stromal cell–derived sEVs from infarcted heart carry cytokines and miRNAs with protumorigenic properties such as TGF-β, galectin-3, and miR-221 to accelerate the growth of lung and colon cancers." (PMID 40915108, 2025). "A form of PEC (the modified citrus pectin) that is able to bind galectin-3 and is highly expressed on the membranes of colon cancer cells was exploited to functionalize calcium phosphate NPs and CS NPs." (PMID 38543324, 2024). "This study reports that galectin-3 secretion by human colon cancer cells induces cancer cell secretion, in an autocrine/paracrine manner, of a number of proteases including cathepsin-B, MMP-1 and MMP-13." (PMID 37055381, 2023). "In contrast, galectin-3 downregulation decreased the motility of human colon cancer cells and human glioblastomas." (PMID 37185758, 2023). "Recently, we showed that platelet GPVI interacts with a tumor-resident galectin-3 through the binding to its collagen-like domain, expressed on the surface of breast and colon cancer cells." (PMID 36873388, 2023). "This study shows that galectin-3 expression and secretion by human colon cancer cells induces cell secretion of several proteases in an autocrine or paracrine manner through activation of PYK2-GSK3α/β signalling." (PMID 37055381, 2023). "One study reported that a knockdown of galectin-3 resensitized multidrug-resistant Caco-2 colon cancer cells to epirubicin by inhibiting ABC transporters." (PMID 36614114, 2022). "Galectin-3 is associated with a lot of cancers, such as mesothelioma, breast, HCC, and colon cancers." (PMID 35069936, 2022). "Revacept inhibited the platelet GPVI and tumor galectin-3 interaction in a colon carcinoma cell line." (PMID 34290095, 2021). "Galectin-3 is a common molecule studied in cancer research, especially in colon cancer, whereas only one study involving an animal model has reported that galectin-3 is associated with GBM progression." (PMID 29378529, 2018). "We also observed that blocking the interaction between galectin-3 with CEA inhibited colon cancer cells migration." (PMID 28977916, 2017).
colon carcinoma (continued). "A previous report indicated that the protein stability of hnRNP Q protein is maintained by Galectin-3 in colon cancer;18 however, the increased mRNA level in tumors is still unclear." (PMID 28079881, 2017). "Although extracellular expression of galectin-3 modulates the various stages of metastasis in human colon cancer, the mechanistic details of its role in intracellular signaling, migration, and metastatic potential of colon cancer cells are unclear." (PMID 28977916, 2017). "To confirm the expression pattern of Galectin-3 in colon cancer, we initially evaluated the mRNA and protein levels in a series of colon rectal cancer (CRC) cell lines." (PMID 28146425, 2017). "High expression of galectin-3 is correlated with the malignant behavior and metastasis of human colon cancer cells." (PMID 28977916, 2017). "Our previous study demonstrated that overexpression of galectin-3 increased colon cancer cell migration by activating the K-Ras-Raf-ERK pathway." (PMID 28977916, 2017). "In the present study, we determined the expression pattern of galectin-3 in colon cancer cell lines and tissue samples, and systematically analyzed the relationships between galectin-3 expression level and clinicopathologic factors." (PMID 28146425, 2017). "In this study, we further verified that siHuR or overHuR modulated the change of chemoresistance of colon cancer cells to Epi through galectin-3/β-catenin signaling." (PMID 28968471, 2017). "Nevertheless, the role and mechanisms of galectin-3 in chemo-sensitivity, invasion and metastasis in colon cancer remain elusive." (PMID 28146425, 2017). "Treatment of CD4 CD8 double-negative T-cells, T-cell leukemia, diffuse large B cell lymphoma and colon cancer cell lines for 4–48 hours with 300–15000 nM Galectin-3 was reported to result in apoptosis of the recipient cells." (PMID 25869099, 2015). "However, our data showed that recombinant galectin-3 has a weaker effect on cancer cell growth than senescent MSCs, suggesting that other cytokines secreted from senescent MSCs may be associated with the stimulation of colon cancer cell growth." (PMID 26273429, 2015). "Lastly, we analyzed the mechanisms of senescent MSCs and galectin-3 on colon cancer cell signal transduction, finding that senescent MSCs and exogenous galectin-3 promoted colon cancer cell growth by activating the MAPK (ERK1/2) pathway." (PMID 26273429, 2015). "Galectin-3 can also mediate nuclear β-catenin accumulation by regulating glycogen synthase kinase-3β (GSK-3β) activity in colon cancer." (PMID 25669973, 2015). "Sialylation of ß1-integrin in colon carcinoma cells has also been shown to block cell adhesion to galectin-3 and to protect against galectin-3-induced apoptosis." (PMID 23468914, 2013). "In this study, we aimed to decipher the galectin-3 molecular mechanisms involved in colon cancer cell drug resistance." (PMID 24303084, 2013). "Galectin-3 upregulates β-catenin expression, increases its nuclear accumulation, and augments Wnt/β-catenin signaling in human colon cancer cells by regulating glycogen synthase kinase-3β (GSK-3β) phosphorylation and activity via the PI3K/Akt pathway." (PMID 24303084, 2013). "LGALS3 is involved in the resistance of human colon cancers by blocking the death-inducing signaling complex (DISC) formation and recruitment of the apoptosis-initiating protease, procaspase-8." (PMID 23865481, 2013). "In colonic cancer tissues, Beclin1 was higher in cancer compared to normal, while galectin-3 was lower compared to normal tissues." (PMID 22039439, 2011). "While galectin-3 demonstrates consistent results as biomarker in gastric cancer, additional research is required to confirm its efficacy as marker in colon cancer." (PMID 23658855, 2010). "While most of the publications reported increased expression, some demonstrated decreased expression of galectin-3 in colon cancer compared to the normal tissue." (PMID 23658855, 2010).